SNAP25 (synaptosome associated protein 25)
Diseases named in the same sentence as SNAP25 in open-access papers (continued):
Sharing a sentence is not in itself a finding about the gene and the disease.
tumor (continued). "Then, immunohistochemistry assay was applied to analyze the SNAP25 expression in surgical resection specimens, from which SNAP25 expression was negatively correlated with the tumor grading (p<0.001, Mann–Whitney test)." (PMID 34490096, 2021). "Immunohistochemistry staining demonstrated that the level of SNAP25 was lower in tumor tissues than in normal tissues." (PMID 32412599, 2020). "The verification via the GEPIA website showed that SNAP25 was highly expressed in normal tissues and lowly expressed in tumor tissues." (PMID 32412599, 2020). "The verification of SNAP25 in GEPIA website showed that SNAP25 was highly expressed in normal tissues compared with tumor tissues." (PMID 32412599, 2020). "Immunohistochemistry staining obtained from the HPA database also demonstrated the deregulation of SNAP25 expression in tumor tissues compared with the normal tissues." (PMID 32412599, 2020). "Furthermore, we harnessed gene ontology (GO) analysis, explored Kyoto Encyclopedia of Genes and Genomes (KEGG) and employed various methodologies to unravel the potential mechanisms underpinning SNAP25’s involvement in tumor development." (PMID 39430761, 2024). "SNAP25 influences tumor progression by activating c-MYC through the MEK/ERK pathway." (PMID 39430761, 2024). "Using the TIMER, we found that SNAP25 affected tumor-infiltrating immune cells in PCa." (PMID 35392903, 2022). "SNAP25 may also be involved in the biological process by which immune cells enter tumor tissue and improve the TME, thereby influencing the development of PCa and patient prognosis." (PMID 35392903, 2022). "This suggests that SNAP25 may increase immune infiltration in PCa by regulating the migration of immune cells in the tumor microenvironment." (PMID 35392903, 2022). "Moreover, the effect of SNAP25 overexpression on tumor growth was also examined by a nude-mouse transplanted tumor model." (PMID 34490096, 2021). "Moreover, upregulated SNAP25 also decreased tumor volume and prolonged the overall survival (OS) of the xenograft mouse." (PMID 34490096, 2021). "The present study showed hub functional terms involved in GBM and speculated that SNAP25 might be a tumor suppressor that could be used as a potential biomarker for GBM treatment." (PMID 32412599, 2020). "Although expression of SNAP25 and integrin αV could be detected in the tumours, integrin αV labelling was often weak, and results for SNAP25 were inconsistent between samples." (PMID 19002168, 2008). "Finally, in vivo experiments further confirmed that SNAP25 knockout can inhibit tumor growth." (PMID 39430761, 2024). "Moreover, cysteine and methione metabolism, amino sugar and nucleotide sugar metabolism as well as alanine, aspartate and glutamate metabolism pathways were significantly differentiated in Lv-SNAP25 and Lv-NC tumor cells, suggesting that glutamine-related metabolism was highly activated." (PMID 34490096, 2021). "Besides, the upregulated SNAP25 could delay tumor growth and extent the overall survival time of the victims in vivo." (PMID 34490096, 2021). "Finally, only the result of SNAP25 was consistent, suggesting that SNAP25 might be the tumor suppressor of GBM." (PMID 32412599, 2020). "DEA results further supported our categorization of the left area as a tumor region, evident from the presence of marker genes such as EGFR, and the right area as cortex, characterized by neural marker genes like SNAP25." (PMID 39179527, 2024). "Given their similar effect on tumor progression, RUNDC3A expression positively correlated with SNAP25 expression in GNEC patients." (PMID 36182960, 2022). "SR-BI removal led to the diminished expression of RAB22a, SNAP25 and VPS25, which suggested reduced generation and secretion of tumor-derived extracellular vesicles." (PMID 30823658, 2019). "By analyzing the Human Protein Atlas, we compared the protein expression of SNAP23, SNAP25, SNAP29 and SNAP47 in ovarian normal and tumor tissues." (PMID 27855700, 2016).
tumor (continued). "The downregulation of SNAP25 significantly inhibited tumor growth compared to the negative control group." (PMID 39430761, 2024). "In fact, the neuronal marker NeuN, the stem factors SOX2 and SNAP25, a genes expressed by GSCs upon recurrence are present in the infiltrative region, whereas SNAP25 is absent and few neurons are present in the tumor core." (PMID 36835628, 2023). "Thus, SNAP25 may play a key role in the regulation of TME in PCa by participating in cellular and humoral immunity and stimulating anti-tumor function." (PMID 35392903, 2022). "Since a similar chemotherapy resistance phenomenon has been observed in multiple NECs and related tumour types, we sought to understand whether SNAP25 plays a similar role in other NECs (including PNET, SINEC and SCLC) and tumours with similar molecular signatures." (PMID 35752613, 2022). "Finally, the validation of SNAP25 in clinical samples using qRT-PCR showed that the expression level of SNAP25 was significantly reduced in tumor tissues compared with normal tissues, which again proved the conclusion above." (PMID 32412599, 2020). "The proapoptotic and anti-tumor activity of BTX-A might not be related to SNAP-25." (PMID 27398270, 2016).
cancer (20 papers, 2010 to 2025). A tumor composed of atypical neoplastic, often pleomorphic cells that invade other tissues. "We investigated the potential underlying mechanisms of synaptosomal-associated protein 25 (SNAP25) in cancer-related signaling pathway, immunity and metabolism progresses through gene set enrichment analysis (GSEA) and TISIDB database." (PMID 33150073, 2020). "In addition, SNAP25 is associated with the pathogenesis of cancers and some diseases affecting the nervous system and immune system in humans." (PMID 38401037, 2024). "Bioinformatic analysis showed that SNAP25 was not only closely associated with the clinical manifestations of PCa, but was also involved in cancer-related signaling pathways as well as immune and metabolic processes, which might provide new targets for studying the underlying mechanisms of PCa." (PMID 35392903, 2022). "Next, we performed immunofluorescence experiments and observed a significant decrease in the expression level of SNAP25 in cancer cells." (PMID 35392903, 2022). "The genes assayed were neuroendocrine-associated genes (INSM1, ASCL1, NRCAM, and SNAP25), one gene centered in the gene regulatory network (NUF2), and five possibly cancer-associated genes (PTP4A3, RFC4, REST, APEH, and FBLN2)." (PMID 34395507, 2021). "GSEA and TISIDB suggested that SNAP25 involved in cancer-related signaling pathway, immunity and metabolism progresses." (PMID 33150073, 2020). "An Oncomine analysis of cancer versus normal tissue revealed that expression of SNAP25 was down-regulated in GBM among different analysis datasets." (PMID 32412599, 2020). "When comes to cancers, SNAP25 functions differently according to various cancer types." (PMID 34490096, 2021). "Contaminants included the cancer genes KRAS (2 samples, including one sample identified by manual review), STAG2 (35 samples), DDX58 (25 samples; DDX58 encodes RIG-I), and SNAP25 (9 samples), some of which can be traced to other projects from the same laboratory." (PMID 34952565, 2021). "For SNAP25, 57 gene sets were enriched, including 11 gene sets which were cancer-related processes." (PMID 33150073, 2020). "Overall, these results indicate that SNAP25 and RUNDC3A expression was coregulated in various cancer types." (PMID 35752613, 2022). "When the DEGs were further compared across four cancer types, we found five coregulated DEGs (upregulated DEGs: PCSK1N, CAMK2B, RUNDC3A and SNAP25; downregulated DEG: DPT) among four NECs." (PMID 35752613, 2022). "Genes such as KIF5A, SOX10, MYL9, TRIM9, MYH11, and SNAP25 are known to play important roles in biological development, suggesting that LRP1B may also be a key factor in cancer." (PMID 40170839, 2025).
psychiatric disorder (18 papers, 2013 to 2025). A disorder characterized by behavioral and/or psychological abnormalities, often accompanied by physical symptoms. "Our data suggest that SNAP-25, NRXN3 and NRGN versus beta-amyloid and phosphorylated tau protein 181 (ptau) are regulated differentially across psychiatric disorders and that SNAP-25 has a moderate diagnostic potential for MDD and SCZ." (PMID 40840974, 2025). "In the PPI network of these Egr targets in the DG region, the top key nodes tightly associated with distinct psychiatric disorders and addictive behaviors in previous studies included Syt1, Stx1a, Dlg4, Cplx1, Gria1, Snap25, Rab3a, and Bdnf81,86–91." (PMID 37758941, 2023). "One possible reason for the relationship between SNAP-25 and these psychiatric disorders is that SNAP-25 has a genetic basis that is linked to some symptoms that co-occur and are common among these disorders." (PMID 37635807, 2023). "We aimed to study a SNAP-25 gene polymorphism, which is related to many psychiatric diseases, and FMS association in this prospective study." (PMID 24885975, 2014). "We aimed to evaluate the SNAP-25 gene (MnlI = rs3746544 and DdeI = rs1051312) polymorphism, which is related to many psychiatric diseases, and FMS association in this prospective study." (PMID 24885975, 2014). "Polymorphic variants of the SNAP-25 gene emerged as putative genetic components of impulsivity, as SNAP-25 protein plays an important role in the central nervous system, and its SNPs are associated with several psychiatric disorders." (PMID 24391914, 2013). "We also aimed to carry out an association study to analyze whether either these loci or the polymorphic variants of the SNAP-25 promoter (rs6077690 AT and rs6039769 AC), studied so far in psychiatric disorders, contribute to the genetic background of impulsivity in a non-clinical sample." (PMID 24391914, 2013). "Synaptosome-associated protein 25 (SNAP25) is a presynaptic membrane-binding protein; it plays a crucial role in neurotransmission and has already been studied in numerous psychiatric disorders." (PMID 38133436, 2023). "Furthermore, correlations between CSF levels of SNAP-25 and AD pathology markers were found to show subtle differences between psychiatric disorders." (PMID 40840974, 2025). "Concordant with the increased inflammatory signal, there was a downregulation in mRNA expression of genes linked to neurodevelopment and myelination, neurotransmitter regulation, and psychiatric disorders including calcium binding Calb2 and S100b, as well as SNAP25, Pvalb, MAG, Olig1, and Olig2." (PMID 40059770, 2025). "The mechanisms by which alterations in SNAP-25 may concur to these psychiatric diseases are still undefined, although alterations in neurotransmitter release have been indicated as potential causative processes." (PMID 27047369, 2016). "Genetic variants of SNAP-25 including promoter polymorphisms, have already been investigated as putative risk factors of other psychiatric disorders as well, but it has not yet been studied in the background of impulsivity in a non-clinical sample." (PMID 24391914, 2013). "For the SNAP-25 itself, although changes in neurotransmitter release have been suggested as potential causative processes, the mechanisms by which abnormalities in SNAP-25 may contribute to certain mental illnesses, including ADHD, remain unclear." (PMID 37635807, 2023). "The second part of the review addresses the known proteins whose aggregation in brain tissue has been observed in psychiatric disorders (amyloid, tau protein, α-synuclein, DISC-1, disbindin-1, CRMP1, SNAP25, TRIOBP, NPAS3, GluA1, FABP, and ankyrin-G)." (PMID 36430976, 2022). "Defects of SNAP-25 may contribute to psychiatric diseases by impacting not only presynaptic but also postsynaptic functions." (PMID 40316481, 2025).
psychiatric disorder (continued). "Studying SNAP-25 expression in CSF samples of a large cohort of clinically well-characterised MDD patients, we observed significantly decreased levels compared with control subjects without signs of mental illness, inflammation or neurodegeneration." (PMID 40840974, 2025).
neurological diseases (16 papers, 2012 to 2025). "We measured CSF SNAP-25, β-synuclein, and neurogranin in 48 untreated PwMS and 50 controls with other neurological diseases (ONDs) and tested their associations with neuropsychological and MRI data." (PMID 39708160, 2024). "We found an interaction between Us9 and Zdhhc17, a palmitoyltransferase of the SNARE protein Snap25, implicated in the regulation of neuronal vesicle-trafficking and associated with neurological diseases such as Huntington’s." (PMID 33370419, 2020). "Among the relatively small number of top rated differentially regulated genes, there were at least 35 genes that have been shown to have neuron-specific functions or associated with various neurological diseases, including Vamp1, Vamp2 and Snap25 (synaptosomal-associated protein 25)." (PMID 30001398, 2018). "Recent genetic studies in humans and some mouse models indicate that alterations in the SNAP-25 gene structure, expression, and/or function directly contribute to these distinct neuropsychiatric and neurological disorders." (PMID 23028951, 2012). "Our analysis confirmed the marked increase of SNAP-25 and Ng CSF levels in patients with CJD compared to other neurological diseases, reflecting the extensive synaptic damage." (PMID 37684653, 2023). "SNAP-25 is another SNARE complex protein that has been investigated in psychiatric and neurological diseases." (PMID 30582321, 2019).
neurodegenerative disease (14 papers, 2017 to 2025). A disorder of the central nervous system characterized by gradual and progressive loss of neural tissue and neurologic function. "Future studies are needed to ascertain whether SNAP‐25 could contribute to the diagnostic differentiation in other neurodegenerative diseases or be used for monitoring the response to disease‐modifying treatments for AD." (PMID 39912369, 2025). "Instead, biomarkers reflecting synaptic dysfunction and/or damage (such as neurogranin, synaptosomal-associated protein 25, SNAP-25, and β-synuclein) have been investigated mostly investigated in cerebrospinal fluid (CSF) samples of patients with neurodegenerative diseases, but are unexplored in MS." (PMID 39708160, 2024). "In neurodegenerative diseases, the increase of SNAP-25 is mostly supposed to be based on synaptic degeneration and loss which is then reflected by increased CSF levels." (PMID 40840974, 2025). "Among them, synaptosome-associated protein 25 (SNAP25), growth-associated protein 43 (GAP43), neurogranin, and synaptotagmin 1 are widely investigated in neurodegenerative diseases." (PMID 38528511, 2024). "The functionality of HSPA8 and GAPDH in modulating the cellular toxicity of expanded polyQ HTT has been well studied, and SNAP25 has been investigated in the context of neurodegenerative diseases." (PMID 35932982, 2022). "The data establishes PSD-95 as a promising CSF marker for neurodegenerative disease synaptic pathology, while SNAP-25 and Ng appear to be somewhat more specific for AD." (PMID 35461266, 2022). "SNAP-25 CSF levels were similarly higher in subjects with AD (114±30 pg/ml) compared to subjects with NeuroDegen diseases (71±24 pg/ml; p<0.0001), NeuroCtrls (91±53 pg/ml; p<0.005), and HC (83±21 pg/ml; p<0.05)." (PMID 35461266, 2022). "In addition, genes associated with multiple neurodegenerative diseases were also overexpressed in PCOS, as SNARE proteins play a crucial role in hormone secretion and neurotransmitter release, with SNAP-25 being a key gene involved in these processes." (PMID 40790236, 2025). "Cerebrospinal Fluid levels of Synaptosomal Associated Protein 25 kDA (SNAP‐25) were elevated in AD and non‐neurodegenerative diseases compared to controls but did not distinguish AD from other neurodegenerative diseases." (PMID 39912369, 2025). "Unlike the other synaptic proteins, for example, neurogranin, SNAP-25, and Syt1, the CSF 14-3-3 protein levels were also increased in other neurodegenerative diseases, which indicates that they could be general markers of neurodegeneration." (PMID 38246483, 2024). "In this regard, recent studies found that CSF levels of synaptosomal-associated protein 25 (SNAP-25) and neurogranin (Ng), both enriched in synapses, might distinguish CJD from other neurodegenerative diseases accurately and have prognostic potential." (PMID 37684653, 2023). "Our results showed that subjects with AD on average had markedly increased PSD-95 and SNAP-25 CSF levels compared to both healthy controls and subjects with other neurodegenerative diseases, further promoting these two proteins as biomarkers for synaptic dysfunction in AD." (PMID 35461266, 2022). "When evaluating synaptic dysfunction biomarkers in CSF, it was demonstrated that SNAP25, 14‐3‐3 zeta/delta, and NPTX2 (neuronal pentraxin), in various combinations, can discriminate AD from other neurodegenerative diseases." (PMID 40613333, 2025). "Depletion of SNAP-25 or Syntaxin1 induces neurodegeneration, and neuronal death respectively suggesting SNARE protein involvement in the pathology of neurodegenerative diseases." (PMID 39773760, 2025). "We conclude that AD subjects on average have higher CSF levels of PSD-95 and SNAP-25 compared to subjects with non-AD neurodegenerative diseases or other neurological conditions." (PMID 35461266, 2022).
neurodegenerative disease (continued). "The modulation of REST/NRSF, its target gene SNAP-25 and BDNF expression by mGluR5 NAM may therefore represent a novel pharmacological tool to halt the progression of HD and potentially other neurodegenerative diseases." (PMID 32859226, 2020). "Our analysis of two clinical cohorts showed that SNAP‐25 could differentiate between patients with AD and the non‐neurodegenerative diseases NPH and VaD but lacked the ability to differentiate between the AD and non‐AD neurodegenerative diseases." (PMID 39912369, 2025). "Furthermore, synaptic loss has been proposed to lead to increased rather than decreased brain SNAP-25 levels in neurodegenerative diseases." (PMID 40840974, 2025). "In conclusion, our results show that SNAP‐25 may be a potential biomarker for differentiating AD from non‐neurodegenerative diseases." (PMID 39912369, 2025). "All neurodegenerative diseases are characterized by synaptic dysfunction to some extent, and it is not clear why SNAP-25 and Ng may be selectively increased in the CSF of AD subjects." (PMID 35461266, 2022). "Therefore, the finding of a potential suppression of SNAP25, with or without ATF3 getting involved, in SOD1-mutant ALS patients might indeed be of importance and point to a general role in neurodegenerative diseases." (PMID 37491426, 2023).